PKP3 (plakophilin 3)
Description:
A component of desmosome cell-cell junctions which are required for positive regulation of cellular adhesion. Required for the localization of DSG2, DSP and PKP2 to mature desmosome junctions. May also play a role in the maintenance of DSG3 protein abundance in keratinocytes (By similarity). Required for the formation of DSP-containing desmosome precursors in the cytoplasm during desmosome assembly. Also regulates the accumulation of CDH1 to mature desmosome junctions, via cAMP-dependent signaling and its interaction with activated RAP1A. Positively regulates the stabilization of PKP2 mRNA and therefore protein abundance, via its interaction with FXR1, may also regulate the protein abundance of DSP via the same mechanism. May also regulate the protein abundance of the desmosome component PKP1 (By similarity). Required for the organization of desmosome junctions at intercellular borders between basal keratinocytes of the epidermis, as a result plays a role in maintenance of the dermal barrier and regulation of the dermal inflammatory response (By similarity). Required during epidermal keratinocyte differentiation for cell adherence at tricellular cell-cell contacts, via regulation of the timely formation of adherens junctions and desmosomes in a calcium-dependent manner, and may also play a role in the organization of the intracellular actin fiber belt (By similarity). Acts as a negative regulator of the inflammatory response in hematopoietic cells of the skin and intestine, via modulation of proinflammatory cytokine production (By similarity). Important for epithelial barrier maintenance in the intestine to reduce intestinal permeability, thereby plays a role in protection from intestinal-derived endotoxemia (By similarity). Required for the development of hair follicles, via a role in the regulation of inner root sheaf length, correct alignment and anterior-posterior polarity of hair follicles (By similarity). Promotes proliferation and cell-cycle G1/S phase transition of keratinocytes (By similarity). Promotes E2F1-driven transcription of G1/S phase promoting genes by acting to release E2F1 from its inhibitory interaction with RB1, via sequestering RB1 and CDKN1A to the cytoplasm and thereby increasing CDK4- and CDK6-driven phosphorylation of RB1 (By similarity). May act as a scaffold protein to facilitate MAPK phosphorylation of RPS6KA protein family members and subsequently promote downstream EGFR signaling (By similarity). May play a role in the positive regulation of transcription of Wnt-mediated TCF-responsive target genes.
Tractability: Antibody: UniProt places it where antibodies can reach, with high confidence; its Gene Ontology location is reachable by antibodies, with high confidence. PROTAC: ubiquitination databases record sites on it.
Gene: Protein-coding gene on chromosome 11 (392,614 to 404,908, forward strand). Ensembl gene ENSG00000184363.
Subcellular location: Nucleus; Cell junction, desmosome; Cytoplasm; Cell membrane; Cell junction, adherens junction; Cell junction, desmosome (Isoform PKP3a); Cell junction, desmosome (Isoform PKP3b)
Subcellular location (Human Protein Atlas): Cell Junctions; Nucleoplasm
Pathways (Reactome):
Developmental Biology: Formation of the cornified envelope; Keratinization
Gene Ontology:
Molecular function: alpha-catenin binding; cadherin binding involved in cell-cell adhesion; cell adhesion molecule binding; enzyme binding; protein binding; cadherin binding
Biological process: desmosome assembly; negative regulation of mRNA catabolic process; positive regulation of cell adhesion; positive regulation of cell-cell adhesion; protein localization to plasma membrane; regulation of translation; actin cytoskeleton organization; cell-cell adhesion; desmosome organization; epithelial cell-cell adhesion; epithelial structure maintenance; positive regulation of cell cycle G1/S phase transition; positive regulation of protein localization; regulation of cytokine production involved in immune response; regulation of hair follicle development; regulation of gene expression
Cellular component: adherens junction; cell junction; cytoplasm; desmosome; nucleoplasm; nucleus; plasma membrane; cell-cell junction; cornified envelope
Genetic constraint (gnomAD): Loss-of-function variants: 66 observed, 61.67 expected, observed/expected ratio (o/e) 1.07, 90% interval 0.88 to 1.31. The synonymous counts are far from expectation, so gnomAD's model fits this gene poorly and the ratio says little. Missense variants: 1,338 observed, 1,012 expected, observed/expected ratio (o/e) 1.32, 90% interval 1.26 to 1.38. Synonymous variants: 638 observed, 457.43 expected, observed/expected ratio (o/e) 1.39, 90% interval 1.31 to 1.49.
Homologues: Orthologues: mouse Pkp3 (93% identical), rat Pkp3 (93% identical), pig PKP3 (92% identical), dog PKP3 (90% identical), guinea pig PKP3 (89% identical), macaque PKP3 (81% identical), chimpanzee PKP3 (66% identical), tropical clawed frog pkp3 (61% identical), zebrafish pkp3b (44% identical), zebrafish pkp3a (43% identical), Caenorhabditis elegans jac-1 (23% identical), Drosophila melanogaster p120ctn (19% identical). Paralogues in human: CTNND2 (28% identical), PKP4 (26% identical), PKP2 (25% identical), ARVCF (25% identical), PKP1 (24% identical), CTNND1 (24% identical).
Diseases named in the same sentence as PKP3 in open-access papers:
PKP3 is named in the same sentence as 51 diseases in open-access papers, as found by Europe PMC text mining. Sharing a sentence is not in itself a finding about the gene and the disease. The quoted sentences say what the papers report.
ovarian carcinoma (8 papers, 2019 to 2024). A malignant neoplasm originating from the surface ovarian epithelium. "For example, in ovarian cancer, PKP3 regulates autophagy and invasion by regulating the MAPK-JNK-ERK1/2-mTOR signaling pathway." (PMID 38200443, 2024). "The involvement of the PKP3 protein has been demonstrated in various cancers, including breast cancer, nasopharyngeal carcinoma, stomach cancer, ovarian cancer, and other tumor types." (PMID 38200443, 2024). "Overexpression of PKP3 has been documented to facilitate the malignant features of ovarian cancer cells." (PMID 37420272, 2023). "In line with this, overexpression of PKP3 in ovarian cancer A2780 cells contributes to a significant activation of the MAPK pathway Inactivating the MAPK pathway can reduce the insulin resistance, which represents an obstacle in the treatment efficacy of PCOS." (PMID 37420272, 2023). "PKP3 shows upregulation in ovarian cancer tissues and its expression serves as a prognostic biomarker for ovarian cancer patients." (PMID 37420272, 2023). "PKP3 is highly expressed in various tumors, such as breast cancer, malignant pleural mesothelioma and ovarian cancer." (PMID 34416901, 2021). "In this study, we found that the expression of PKP3 mRNA and protein was upregulated in ovarian cancer and significantly correlated with PFS in patients with ovarian cancer." (PMID 33088217, 2020). "It is enough to prove that PKP3 plays a crucial role in prognosis evaluation and potential therapeutic target of ovarian cancer, but the specific mechanism remains to be further explored." (PMID 33088217, 2020). "In Bonome’s dataset, the level of PKP3 mRNA was also upregulated in ovarian carcinoma compared with normal group (Fold change = 2.459, P = 4.35E−09)." (PMID 33088217, 2020). "The previous studies found that MARCH5 and PKP3 regulated the autophagy and invasion of ovarian cancer." (PMID 30987661, 2019). "Immunohistochemistry and gene knockdown studies showed OV expression of PKP3 and repression of apoptosis through silencing of death receptors (DRs) 4/5 by C-terminal-binding protein 2 in ovarian cancer cell lines, suggesting a role of these two proteins in the disease's progression." (PMID 39309198, 2024). "In addition, enforced PKP3 expression is capable of facilitating the proliferation, formation, and invasion of ovarian cancer cells, which shares correlation with the activated MAPK pathway." (PMID 37420272, 2023). "Here, authors identified eight genes, including PPL and PKP3, whose increase expression in human melanoma metastases and ovarian cancers was associated with a lack of Th1 immune signatures and further strongly correlated with shorter overall survival." (PMID 34060699, 2021). "Recent studies have shown that PKP3 participates in the progression and metastasis of ovarian cancer, prostate cancer and nasopharyngeal carcinoma, but its molecular mechanism underlying the regulation of antitumor immunity remains unclear." (PMID 34416901, 2021). "In addition, PKP3 regulated autophagy and invasion of ovarian cancer through MAPK/JNK/ERK1/2/mTOR signaling pathway." (PMID 33088217, 2020). "Plakophilin 3 in ovarian cancer tissue modulates autophagy through the JNK/ERK/mTOR pathways." (PMID 31358050, 2019). "PKP3 could participate in the invasion and metastasis of ovarian cancer." (PMID 33088217, 2020).
lung carcinoma (7 papers, 2018 to 2024). "Overexpression of adhesion molecules such as PKP3 could be demonstrated to be associated with differential infiltration of various immune cells in human lung cancer tissue, making the demosome status a potential biomarker in the context of immunotherapies." (PMID 34415821, 2022). "Further studies also confirmed that FERMT1 regulates the invasion and migration of lung cancer through PKP3." (PMID 38200443, 2024). "CircIGF2BP3/PKP3 inhibition increased the efficacy of anti-PD-1 treatment in lung cancer mouse model." (PMID 36545327, 2022). "Altered expression of PKP3 transcripts has already been described in connection with lung cancer and other cancer types." (PMID 34415821, 2022). "This suggests that the region in the PKP3 gene body is a functional promoter in lung tissues which is hypermethylated upon inflammation and variably methylated in the context of lung cancer." (PMID 34415821, 2022). "Among these proteins, we selected seven candidates (PC, keratin 18, heat shock 70 kDa protein-8, lectin galactoside-binding soluble 3 binding protein, DNA-dependent protein kinase catalytic subunit, plakophilin-3, cortactin) that have been known to participate in lung cancer progression." (PMID 34249688, 2021). "Moreover, according to previous reports, PKP3 is dysregulated in lung cancer." (PMID 29855376, 2018).
breast carcinoma (6 papers, 2021 to 2025). "Taken together, our results identify a targetable a clinically accessible PKP3-clusterin axis that disrupts circadian gene expression in fat tissue in breast cancer." (PMID 41408487, 2025). "A study on breast cancer revealed that PKP3 exhibited higher expression levels in tumor tissues and showed a positive correlation with node positivity and histologic grade." (PMID 37760912, 2023).
lung adenocarcinoma (6 papers, 2011 to 2025). A carcinoma that arises from the lung and is characterized by the presence of malignant glandular epithelial cells. "The findings showed that PKP3 mRNA was significantly elevated in 15 tumor types, including breast invasive carcinoma, lung adenocarcinoma, and pancreatic adenocarcinoma." (PMID 37760912, 2023). "In non-small cell lung tumours, which include lung adenocarcinomas and squamous cell carcinomas, PKP3 is described as an oncogene, which has the potential as a prognostic marker but also in the therapeutic area." (PMID 34415821, 2022). "Among them, the most significant gene was DNM1L, which concurred with high expression of PKP3 and DNM1L associated with poor survival in lung adenocarcinoma patients." (PMID 24369726, 2013). "The expression of miR-10b-5p is significantly elevated in lung adenocarcinoma (LUAD) tissues, where it promotes cancer progression by directly targeting plakophilin 3 (PKP3) and suppressing the RIPK3/MLKL necroptosis signaling pathway." (PMID 41267084, 2025). "DNM1L was associated with poor survival in lung adenocarcinoma patients when co-expressing with PKP3, and nuclear expression of DNM1L was correlated with not only poor prognosis for lung adenocarcinoma but also drug resistance during hypoxia." (PMID 24369726, 2013).
gastric cancer (5 papers, 2011 to 2024). A primary or metastatic malignant neoplasm involving the stomach. "Decreased Plakophilins (PKP2 and PKP3) may be early prognostic markers and loss of PKP3 expression during gastric carcinoma progression may indicate an invasive phenotype." (PMID 23919729, 2013). "Decreased PKP2 and PKP3 may be early prognostic markers and loss of PKP3 expression during gastric carcinoma progression may indicate an invasive phenotype." (PMID 21194493, 2011). "In our study, we examined PKP1, PKP2, and PKP3 expression and their clinicopathological correlation with gastric cancer." (PMID 21194493, 2011). "We explored the relationship between plakophilins (PKP1, PKP2, PKP3) to gastric cancer via immunohistochemical techniques." (PMID 21194493, 2011). "In light of these data, we suggest that during gastric carcinoma progression, the loss of PKP2 and PKP3 expression correlates with an invasive phenotype." (PMID 21194493, 2011). "However, some studies have shown that PKP3 was significantly downregulated in gastric cancer and bladder cancer, and downregulation of PKP3 promoted the progression and invasion of tumors." (PMID 33088217, 2020). "We observed cytoplasmic staining for PKP1, PKP2, and PKP3 in gastric carcinoma." (PMID 21194493, 2011). "In gastric cancer, PKP1 expression was unchanged but PKP2 and PKP3 were significantly decreased as compared to normal controls." (PMID 21194493, 2011).
melanoma (5 papers, 2018 to 2024). A malignant, usually aggressive tumor composed of atypical, neoplastic melanocytes. "As the expression levels of DSC2, DSC3, DSG1, KRT6B, PKP1, and PKP3 increased, the overall survival time of trunk subtype melanoma patients significantly decreased." (PMID 38660305, 2024). "Our analysis, grounded in WGCNA and PPI networks, identified six genes (DSC2, DSC3, DSG1, KRT6B, PKP1, PKP3) with pivotal roles in melanoma’s oxidative stress response and immune infiltration." (PMID 38660305, 2024). "Interestingly, there are 2 RNA expression patterns of catenins in TCGA-SKCM, where PKP1, JUP, PKP3 belong to the same group and are deleterious for survival in melanoma patients." (PMID 37924160, 2023). "In TCGA-SKCM, we found that the collective up-regulation of JUP, PKP1, and PKP3 could define a distinct catenin subgroup in melanoma (C2), which possesses poorer survival and more aggressive clinical features compared to another subgroup (C1)." (PMID 37924160, 2023). "The results indicate that in trunk subtype melanomas, the protein expression levels of DSC2, DSC3, DSG1, KRT6B, PKP1, and PKP3 are significantly higher than those in adjacent normal samples, suggesting the crucial roles of these central genes in SKCM progression." (PMID 38660305, 2024). "PKP3 expression was revealed to be markedly elevated in melanoma metastasis lacking immune gene signature and was strongly associated with decreased patient survival." (PMID 37251404, 2023).
non-small cell lung carcinoma (5 papers, 2020 to 2024). A group of at least three distinct histological types of lung cancer, including non-small cell squamous cell carcinoma, adenocarcinoma, and large cell carcinoma. "Many researchers have found that the expression of PKP3 was significantly increased in non-small cell lung cancer and prostate cancer, and associated with the prognosis and progression of tumors." (PMID 33088217, 2020). "Moreover, METTL3 increased the expression of circIGF2BP3 through m6A modification, and further enhanced the expression of PD-L1 through the miR-328-3p/miR-3173-5p/PKP3/OTUB1 pathway, ultimately leading to immune escape in non-small cell lung cancer." (PMID 38632251, 2024). "In non-small cell lung cancer (NSCLC), METTL3 mediates m6A modification of the circIGF2BP3 (hsa_circ_0079587) gene in a YTHDC1-m6A-dependent manner, which competitively upregulates PKP3 expression." (PMID 36960074, 2023).
tuberculosis (4 papers, 2016 to 2022). A chronic, recurrent infection caused by the bacterium Mycobacterium tuberculosis. "Low vitamin-Dlevels combined with PKP3-SIGIRR-TMEM16J host variants is associated with tuberculosis and death in HIV-infected and -exposedinfants." (PMID 35083399, 2021). "It has also been reported thatrs10902158 at the PKP3-SIGGIR-TMEM16J genetic locus belongs to a haplotype race-specifically associated with tuberculosis." (PMID 35083399, 2021). "The ANO9 gene, also known as TMEM16J (anoctamin 9), together with the SIGIRR and the PKP3 genes constitute a polymorphic complex associated with susceptibility to tuberculosis." (PMID 31480266, 2019). "It is interesting to note that frequent polymorphisms in the region comprising PKP3, SIGIRR and another gene, TMEM16J, have been linked to susceptibility to tuberculosis, another inflammatory lung disease." (PMID 34415821, 2022).
prostate carcinoma (3 papers, 2020 to 2023). A carcinoma that arises from epithelial cells of the prostate gland. "PKP3 performs an essential function in the prostate cancer tumor microenvironment by regulating invasion of the cell and tumor formation through the MMP7 protein." (PMID 37760912, 2023). "PKP3 functions in the tumor microenvironment of prostate cancer, regulating invasion of the cell and development of the tumor through the MMP7 protein, and is associated with poor patient prognosis." (PMID 37760912, 2023). "In addition, the upregulation of PKP3 in prostate cancer cells leads to an increased proliferation rate." (PMID 37760912, 2023). "PKP3 is related to the carcinogenicity and aggressiveness of prostate cancer." (PMID 35075375, 2022). "The most interesting 8 prognostic biomarkers for prostate cancer included lncRNA LINC01082, miRNA hsa-miR-133a-3p, and genes TTLL12, PTGDS, GAS6, CYP27A1, PKP3, and ZG16B." (PMID 35075375, 2022). "We constructed ceRNA networks in the prostate cancer microenvironment and identified lncRNA LINC01082, miRNA hsa-miR-133a-3p, and genes TTLL12, PTGDS, GAS6, CYP27A1, PKP3, and ZG16B as the potential biomarkers to predict prognosis for prostate cancer." (PMID 35075375, 2022). "lncRNA LINC01082, miRNA hsa-miR-133a-3p, and genes TTLL12, PTGDS, GAS6, CYP27A1, PKP3, and ZG16B are the top RNAs having the potential to predict prognosis for prostate cancer." (PMID 35075375, 2022). "Finally, survival analysis, biological function analysis, and literature researched identified 8 key biomarkers (lncRNA LINC01082, miRNA hsa-miR-133a-3p, mRNA TTLL12, PTGDS, GAS6, CYP27A1, PKP3, and ZG16B) to predict prostate cancer prognosis." (PMID 35075375, 2022).
bladder cancer (2 papers, 2020 to 2023). "As yet, the role of PKP4 in bladder cancer is not known and other members of this family play a variable role, e.g., PKP2 is upregulated and PKP3 is downregulated in invasive bladder cancer." (PMID 36672328, 2023).
colon cancer (2 papers, 2015 to 2022). "PKP3 expression is known to decrease in high grade poorly differentiated oropharyngeal cancer, colon cancer, gastric cancer and bladder cancers." (PMID 25875355, 2015). "When PKP3 levels in normal colon samples were compared with that in colon cancer, the levels were found to be unchanged, while MMP7 levels were higher in colon cancer samples." (PMID 25875355, 2015).
endometriosis (2 papers, 2022 to 2023). The growth of functional endometrial tissue in anatomic sites outside the uterine body. "Interestingly, aberrant methylation and expression of PKP3 has been associated with endometriosis, which is an inflammatory disease of the endometrium and has been observed in the mucosa of ulcerative colitis patients with and without cancer." (PMID 34415821, 2022). "The difference in the results of dataset GSE7305 demonstrated that all NRDEGs were statistically significant, and the expression levels of C7, HOOK1, PKP3, AHR, GJB1, and MYO6 in different groups of endometriosis dataset GSE7305 were statistically significant (P < 0.001)." (PMID 37817158, 2023).